CD44 (CD44 molecule (IN blood group))
Diseases named in the same sentence as CD44 in open-access papers (continued):
Sharing a sentence is not in itself a finding about the gene and the disease.
gout (4 papers, 2019 to 2023). A condition characterized by painful swelling of the joints, which is caused by deposition of urate crystals. "Taken together, our in-vivo findings strongly support that CD44 is essential to the pathogenesis of gout, and pharmacological manipulation of its role is efficacious in models of acute urate crystal induced inflammation." (PMID 32238827, 2020). "In this study, we provided evidence supporting that CD44 expression is enhanced under conditions characteristic of gout and that the CD44 receptor is directly involved in initiating inflammation by MSU crystals in macrophages via facilitating the phagocytosis of MSU crystals." (PMID 31877739, 2019). "CD44 is a transmembrane glycoprotein that is highly expressed in tissue macrophages and may be involved in gout pathogenesis." (PMID 31877739, 2019). "CD44 plays a biologically significant role in mediating phagocytosis of MSU and downstream inflammation and is a novel target in gout treatment." (PMID 32238827, 2020).
Huntington disease (4 papers, 2020 to 2024). Huntington disease (HD) is a rare neurodegenerative disorder of the central nervous system characterized by unwanted choreatic movements, behavioral and psychiatric disturbances and dementia. "CBG treatment also prevented 3‐NP‐induced neuronal loss, recovered catalase, SOD and GSH, compared with control, and down‐regulating genes that were directly associated with Huntington's disease including sgkl, Cd44, and normalized levels of huntingtin‐associated protein‐1." (PMID 32608035, 2020). "In a study of the human cingulate gyrus in Huntington disease, RNA sequencing revealed an upregulation of CD44 during the disease." (PMID 38247821, 2024). "CBG treatment led to the downregulation of Cd44 and Sgk1, suggesting potential normalization of gene expression related to Huntington’s disease physiopathology." (PMID 38891938, 2024). "A specific Huntington’s disease array analysis identified Cd44 and Sgk1 as significantly upregulated genes in 3NP mice." (PMID 38891938, 2024).
hyperglycaemia (4 papers, 2015 to 2025). "Our data similarly showed upregulation of GFAP and CD44, indicating reactive gliosis in response to hyperglycaemia." (PMID 41419458, 2025). "We found OPN was mainly expressed in both Muller and microglia, whereas its receptor, CD44, was up-regulated in microglia by hyperglycemia." (PMID 34434927, 2021). "Hyperglycemia reduces the amount of HA in the glycocalyx (e.g., through degradation by hyaluronidase), leaving less HA available to bind to CD44." (PMID 26448756, 2015). "Possible roles of newly recognized, cross-linked forms of HA, and interactions of a major HA receptor (CD44) with cytokine/growth factor receptors during hyperglycemia, are also discussed." (PMID 26448756, 2015). "Interestingly, astrocyte markers (CD44, KCNJ10, and TGFBR2) were upregulated under hyperglycaemia in the NGS dataset." (PMID 41419458, 2025). "However, astrocyte markers, including CD44, KCNJ10, TGFBR2, GFAP, and S100β, were upregulated under hyperglycaemia, as shown by both NGS transcriptomic analysis and immunostaining." (PMID 41419458, 2025).
injury (4 papers, 2014 to 2021). Damage inflicted on the body as the direct or indirect result of an external force, with or without disruption of structural continuity. "Thus, repair of full thickness excisional skin wounds is delayed in RHAMM−/− mice and CD44 is required for efficient response to sterile skin injury, keratinocyte proliferation and angiogenesis." (PMID 24551108, 2014). "rhPRG4 reduced neuroinflammation and influx of monocytes in a rat model of traumatic brain injury, mediated by its regulation of the ERK1/2 pathway, downstream of CD44 and TLR2/4 engagements." (PMID 34992596, 2021). "After kidney injury, VCAM-1, GFP, SDF -1/CXCR4, and CD44 are upregulated in the injured tissue, which may play important roles in the migration of MSCs to the damaged area." (PMID 33424979, 2020).
Lewis lung carcinoma (4 papers, 2014 to 2025). "The in vitro studies on NPs uptake in CD44+ mouse Lewis lung carcinoma (LLC) cells confirmed NP targeting capability through the recognition of HA and consequent CD44-mediated endocytosis." (PMID 36139623, 2022). "Based on the gating parameters, we noted that the tumor-retrieved cells were mainly composed of CD44+ Lewis lung carcinoma (LLC) cells." (PMID 24581230, 2014).
liver cirrhosis (4 papers, 2014 to 2020). "CD133 expression could be more sensitive than CD44 expression to the composition changes in the process of HCC with liver cirrhosis, which might cause this difference in expression." (PMID 27329727, 2016).
malignant mesothelioma (4 papers, 2018 to 2023). A malignant neoplasm of the pleura or peritoneum, arising from mesothelial cells. "In malignant mesothelioma the expression of CD44, alone or in association with other molecules, has been mainly investigated as marker of disease, not for therapeutic potential." (PMID 37398648, 2023). "Similarly, in malignant mesothelioma (MM) cells, YAP/TEAD activates CD44 transcription by binding to the CD44 promoter at TEAD-binding sites, while CD44 regulates Merlin phosphorylation and sequentially promotes YAP transcriptional co-activator." (PMID 30935014, 2019).
metastatic melanoma (4 papers, 2019 to 2024). A melanoma that has spread from its primary site to another anatomic site. "NRAS produces splice variants that are more immunogenic than canonical proteins encoded by the same gene with missense mutations, and the number of CD44 variants is further increased in metastatic melanoma." (PMID 38462618, 2024). "We examined two potential targets for our drug payload, CD44 and IGFR1 which are both implicated in the progression of metastatic melanoma." (PMID 30824801, 2019).
mucinous carcinoma (4 papers, 2013 to 2025). "Furthermore, the expression of CD44 was significantly associated with nuclear grade (p = 0.003) and subtype of EC (p = 0.012 for the various histological type comparisons, and p = 0.019 when comparing type I EC [EmAC G1 and G2] plus mucinous carcinoma with type II EC (CC, SC) plus EmAC G3)." (PMID 30372483, 2018).
oligodendroglioma (4 papers, 2023 to 2025). A well-differentiated (WHO grade II), diffusely infiltrating neuroglial tumor, typically located in the cerebral hemispheres. "CD44 was found in 100% and 85% of gliomatosis cerebri and oligodendroglioma respectively, and in 50%–78% of other tumors." (PMID 39473196, 2024).
oral epithelial dysplasia (4 papers, 2014 to 2025). "The study highlighted the importance of using CD44 as a predictive marker for assessing risk and monitoring oral epithelial dysplasia." (PMID 40005368, 2025). "Further studies seem to be necessary on the function and expression of CD44 and TGF-B as therapeutic targets for premalignant oral lesions and OSCC." (PMID 33681421, 2021). "Comparison of ALDH1, SOX2, CD44, and OCT4 Values between p16-positive and p16-negative Oral Epithelial Dysplasia." (PMID 34709167, 2021). "Further studies are required to investigate the function and expression of CD44 and TGF-B as therapeutic targets for management of premalignant oral lesions and OSCC." (PMID 33681421, 2021). "The mean expression scores of CD44 were 268.4 ± 13.5, 240.8 ± 20.4, and 191.6 ± 18.3 in OSCC, oral epithelial dysplasia, and normal mucosa, respectively; CD44 staining too demonstrated a significant difference between the OSCC and normal oral mucosa (P < 0.001)." (PMID 24883329, 2014).
ovarian serous cystadenocarcinoma (4 papers, 2016 to 2025). A malignant serous cystic epithelial neoplasm arising from the ovary. "Positive correlations have been found between the gene expression of integrin αV (ITGAV) and PD-L1 (CD274) or CD44 in ovarian serous cystadenocarcinoma from the OncoDB online database." (PMID 40093794, 2025). "CD44 showed positive relation to the sub-immune checkpoint in most cancers, including TGCTs, adrenocortical carcinoma (ACC), KICH, LGG, LIHC, LUAD, and ovarian serous cystadenocarcinoma (OV)." (PMID 38590654, 2024). "Recent studies have shown that FBXL7 expression was positively correlated with CD44, PDGFA, PDGFC, and PDGFD in ovarian serous cystadenocarcinoma." (PMID 30301218, 2018). "The results showed that FBXL7 expression was positively correlated with CD44, PDGFA, PDGFC, and PDGFD in ovarian serous cystadenocarcinoma tissues with a statistical significance (p = 0.001 or p < 0.001)." (PMID 30301218, 2018). "In addition, FBXL7 expression was positively correlated with CD44, PDGFA, PDGFC, and PDGFD in ovarian serous cystadenocarcinoma." (PMID 30301218, 2018).
pancreatitis (4 papers, 2016 to 2025). Inflammation of the pancreas. "Further investigations, including differential expression analysis and machine learning techniques, revealed six significant diagnostic markers for pancreatitis: RAP1GDS1, TOP2A, ADK, POLL, CD44, and CD4." (PMID 40787634, 2025). "We then conducted qRT-PCR on serum samples from five pancreatitis patients and five healthy controls to examine the expression levels of RAP1GDS1, TOP2A, ADK, POLL, CD44, and CD4." (PMID 40787634, 2025). "In our study, we identified key hypoxia-related genes—RAP1GDS1, TOP2A, ADK, POLL, CD44, and CD4—in pancreatitis samples using methods such as WGCNA, XGBoost, and RF algorithms." (PMID 40787634, 2025). "Our study found increased soluble CD44 plasma levels in patients with septic shock four days after admission, while no change was noted in patients with pancreatitis." (PMID 40885913, 2025).
prostatic small cell neuroendocrine carcinomas (4 papers, 2011 to 2020). "Indeed, those cells are immunohistochemically characterized by the expression of CD44, a stem cell marker commonly reported and believed to be more specific for small cell carcinoma of the prostate." (PMID 22110988, 2011). "Initially described as a poorly differentiated adenocarcinoma, PC3 was further demonstrated to express typical features of prostatic small-cell neuroendocrine carcinoma including AR and PSA absence, neuroendocrine and CD44 marker expression, and androgen independency." (PMID 32313004, 2020). "Furthermore, overexpression of CD44 enhances glycolytic activity in the highly aggressive prostate small cell neuroendocrine carcinoma (SCNC) via PFKFB4 upregulation, whereas knockdown of CD44 by RNA interference increases the sensitivity of SCNC cells to carboplatin." (PMID 33335857, 2020).
seminoma (4 papers, 2017 to 2024). A radiosensitive malignant germ cell tumor found in the testis (especially undescended), and extragonadal sites (anterior mediastinum and pineal gland). "This coincides with our data on the increased expression of CD44 in tumor stromal cells and stromal components in TGCTs and the association of CD44 expression with the aggressive behavior of seminomas." (PMID 38796656, 2024). "We demonstrate that CD44 is over-expressed in TGCTs and in tumor stroma compared to normal tissue and it is associated with diverse biological outcomes in seminomas and NSGCTs." (PMID 38796656, 2024). "The increased expression of CD44 in seminoma cells as well as in tumor stroma is positively associated with clinicopathological variables such as tumor size, nodal metastasis, vascular/lymphatic invasion, and disease stage." (PMID 38796656, 2024). "Positive CD44 staining in tumor cells and stromal components was associated with increased tumor size, the presence of nodal infiltration, elevated vascular/lymphatic invasion, and advanced stage of disease in seminomas." (PMID 38796656, 2024). "The increased expression of CD44 either in tumor cells or in stromal components was associated with tumor size, nodal metastasis, vascular/lymphatic invasion, and disease stage only in seminomas." (PMID 38796656, 2024). "By evaluating HM27 and HM450 arrays to measure the level of methylation at known CpG sites of CD44 gene we found an inverse correlation between methylation of the 5’UTR in the first exon and in the gene body and CD44 expression in seminomas." (PMID 38796656, 2024). "In seminomas, a high percentage of tumor and stromal cells showed cytoplasmic and/or cell surface staining for CD44 as well as increased staining for CD44 in the tumor stroma was found in some cases." (PMID 38796656, 2024). "Western blot analysis confirmed that JKT-1 seminoma cells also expressed higher protein levels of the standard isoform of CD44 (CD44s) compared to NTERA-2/D1(NT2/D1) and NCCIT cells." (PMID 38796656, 2024). "Although CD44 is expressed almost equally in seminomas and NSGCTs, it is correlated with aggressiveness only in seminomas." (PMID 38796656, 2024). "CD44 staining was detected both at the cell membrane and in the cytoplasm of tumor cells in seminomas and NSGCTs." (PMID 38796656, 2024). "We found that the elevated expression of CD44 in seminomas and stromal staining are related to tumor aggressiveness only in seminomas." (PMID 38796656, 2024). "Positive staining for CD44 was found in tumor cells, stromal components, or both in seminoma and NSGCTs." (PMID 38796656, 2024). "The expression of CD44 is significantly higher either in seminomas or in NSGCTs samples compared to normal tissues." (PMID 38796656, 2024). "The expression of CD44 in tumor cells as well as in tumor stroma fosters an aggressive phenotype in seminomas and should be considered in disease treatment." (PMID 38796656, 2024). "We found that all tumor cells expressed CD44 and the higher mRNA levels were detected in seminoma JKT-1 cells compared to embryonal carcinoma NTERA-2/D1(NT2/D1), and NCCIT cells." (PMID 38796656, 2024). "We mined data on the expression of CD44 in 137 patients with TGCTs, including 68 seminomas and 68 NSGCTs and 165 normal tissues by using Gene Expression Profiling Interactive Analysis 2 (GEPIA2)." (PMID 38796656, 2024). "Analyses of publicly available datasets reveal elevated mRNA levels of CD44 either in seminomas or in NSGCTs compared to normal tissues." (PMID 38796656, 2024). "The elevated expression of CD44 in tumor and stromal cells and ECM components in seminoma is associated with tumor size, nodal metastasis, vascular/lymphatic invasion, and disease stage." (PMID 38796656, 2024). "Positive CD44 staining was found in stromal components in 16 out of 33 patients with seminoma and in 10 out of 38 patients with NSGCTs." (PMID 38796656, 2024).
seminoma (continued). "All these data reveal diverse biological functions of CD44 in the progression of seminomas and NSGCTs." (PMID 38796656, 2024). "In another study with a limited number of patients, CD44 expression was also detected in NSGCTs and interestingly it was reported that apart from the standard isoform of CD44 (CD44s) expressed in seminomas, a high molecular weight isoform of CD44 (CD44v8-10) was expressed in NSGCTs." (PMID 38796656, 2024). "Our data suggest a distinct tumor-promoting role for CD44 in seminomas." (PMID 38796656, 2024). "We found that seminomas and NSGCTs cell lines express high levels of the standards isoform of CD44." (PMID 38796656, 2024). "Interestingly, we noticed a positive correlation between methylation from 0 to 200 bases upstream of the transcriptional start site (TSS200) and CD44 expression in seminomas." (PMID 38796656, 2024). "CD44 may exhibit diverse biological functions in seminomas and NSGCTs." (PMID 38796656, 2024). "According to stromal CD44 staining, both stromal cells and ECM in seminomas and in NSGCTs were positive." (PMID 38796656, 2024). "Previous studies have shown that CD44 is expressed in seminomas and not in normal germ and stromal cells and in peritubular connective tissue." (PMID 38796656, 2024). "Most seminomas (24 out of 33) found negative for CD44 staining in tumor cells (≤10% tumor cell positivity), whereas only 9 out of 33 seminomas were positive for CD44 expression (>10% tumor cell positivity)." (PMID 38796656, 2024). "In GCTs, each analyzed entity displayed an individual marker expression profile, with ECs mainly presenting as CD24strong/CD44+/CD133+/CD184‐, seminomas as CD24‐/CD44+/CD133+/CD184+, YSTs as CD24weak/CD44‐/CD133‐/CD184+, and CCs as CD24weak/CD44‐/CD133‐/CD184‐." (PMID 34293822, 2022). "Positive staining was demonstrated in seminoma for Nanog (red), OCT4 (brown), and SALL4 (brown); skin for SOX2 (brown); and tonsil for pSTAT3 (brown) and CD44 (brown)." (PMID 29046873, 2017).
steatosis (4 papers, 2013 to 2025). Increased lipid within the cytoplasm of cells. "Livers of B6, Ccr2−/− and Cd44−/− mice each developed significant and equivalent histological evidence of moderate steatosis as demonstrated by oil-red-O staining and histopathological scoring." (PMID 23762326, 2013). "Taken together, these data indicate that Ccr2−/− are completely protected and Cd44−/− mice are partially protected from hepatic inflammation despite similar histological evidence of steatosis and serological evidence of hepatocellular damage when compared to B6 mice." (PMID 23762326, 2013). "In addition, soluble CD44 at the serum level was shown to be elevated with the severity of steatosis, and the level of soluble CD44 was higher in NASH patients than in those without NASH." (PMID 38790021, 2024).
synovial sarcoma (4 papers, 2019 to 2023). "Post-minus pre-treatment increase in CD44 staining intensity was negatively correlated with post-treatment SUVmax, and was higher in synovial sarcomas than the other diagnoses." (PMID 30999901, 2019). "When we consider synovial sarcoma, CD44 is detected in biopsies but not in studies with induction media on the populations obtained." (PMID 37173919, 2023). "Studies of immunohistochemistry determined that CD44 expression did not correlate with prognosis (survival, local recurrence, or metastasis) in synovial sarcoma." (PMID 35785191, 2022). "However, this study confirmed that ALDH1 positive synovial sarcomas had a significantly poorer prognosis compared to ALDH1 negative synovial sarcomas, providing an alternative prognosis marker to CD44." (PMID 35785191, 2022).
tendinopathy (4 papers, 2017 to 2024). "Decreased senescence and SASP via overexpression of CD44 can ameliorate rat experimental tendinopathy." (PMID 36077161, 2022). "We propose compensative and anti-senescent roles of CD44 in tendinopathy." (PMID 38309291, 2024). "Taken together, the regulation between CD44 and miR-146a is worth exploring in tendinopathy, and AKT might be a critical signaling regulator between CD44 and miR-146a." (PMID 38309291, 2024).
thyroid (4 papers, 2012 to 2025). "Although direct evidence linking CD44 to TC remains limited, the protein’s well-established functions in other malignancies justify further exploration of its potential role in thyroid tumorigenesis, resistance to therapy, and clinical outcomes." (PMID 40363706, 2025).
tuberculosis (4 papers, 2016 to 2024). A chronic, recurrent infection caused by the bacterium Mycobacterium tuberculosis. "CD44 acts as a macrophage binding site for the attachment of Mycobacterium tuberculosis, leading to macrophage recruitment against tuberculosis." (PMID 35153741, 2021). "In the DS tuberculosis model, double immunization with TB/FLU-06E at the start of the HR therapy resulted in a significantly higher level of total spleen-derived cytokine-producing CD4+ and CD8+ Tem cells (CD44+ CD62L-), with a markedly higher proportion of IFN-γ and IFN-γ,TNF-α producing cells." (PMID 39065554, 2024).